IL22 (interleukin 22)
Diseases named in the same sentence as IL22 in open-access papers (continued):
Sharing a sentence is not in itself a finding about the gene and the disease.
renal fibrosis (10 papers, 2017 to 2024). A final common manifestation of a wide variety of chronic kidney diseases characterized by glomerulosclerosis and tubulointerstitial fibrosis. "In summary, our findings suggest that anti-ANGPTL3/IL22 fusion protein protects the kidney by reducing proteinuria and renal fibrosis as well as stabilizing the endocrine environment in the treatment of DN." (PMID 36544775, 2022). "In contrast, when mice were treated with IL‐22, renal fibrosis and histopathology were significantly improved, as well as kidney functions." (PMID 33634980, 2021). "Histological staining in chronic tubular atrophy showed diffused increasing renal fibrosis (extensive green-bluish areas in Masson’s trichrome staining) after 14 days of rCOC, and a moderate increase in IL-22 positive cells after 14 days of rCOC." (PMID 29054964, 2017). "In brief, our data indicated that renal fibrosis, especially glomerular fibrosis, was significantly attenuated after IL-22 gene therapy in established DN." (PMID 28726774, 2017). "In summary, this study provided new evidence for a better understanding of the biological activities of IL-22 in DN in terms of protection against renal fibrosis and NLRP3 inflammasome activation." (PMID 28726774, 2017). "Immunohistochemical staining of collagen IV and fibronectin was performed to further clarify the effect of IL-22 on renal fibrosis." (PMID 28726774, 2017). "Simultaneously, IL-22 gene therapy drastically alleviated renal fibrosis and proteinuria excretion in DN." (PMID 28726774, 2017). "Furthermore, through the NLRP3/caspase-1/IL-1β pathway, IL-22 can reverse the overexpression of fibronectin, collagen IV, and extracellular matrix in mouse renal glomerular mesangial cells, thereby ameliorating renal fibrosis and proteinuria excretion in DN." (PMID 36776877, 2023). "Notably, IL-22 intervention significantly alleviated renal fibrosis and dysfunction in AA-induced nephropathy." (PMID 31616439, 2019). "Notably, we found that IL-22 possessed potentials to ameliorate renal fibrosis in the short-term mouse model of AAN." (PMID 31616439, 2019). "In contrast, administration of IL-22 significantly downregulated the renal overexpression of Fibronectin, Collagen IV, Vimentin, and α-SMA, suggesting that IL-22 intervention could alleviate renal fibrosis in AAN." (PMID 31616439, 2019). "In this study, we found that IL-22 gene therapy could attenuate renal fibrosis through inhibition of ECM accumulation and mesangial matrix expansion in DN, thus largely preserving renal function of diabetic mice." (PMID 28726774, 2017). "The anti-IL-22 could reduce inflammation and renal fibrosis in Ang II-treated mice." (PMID 38345042, 2024). "In addition, IL-22 can ameliorate renal fibrosis and attenuate microalbuminuria in DKDs." (PMID 36776877, 2023). "Taken together, anti-ANGPTL3/IL22 significantly moderated kidney collagen accumulation and suppressed the expression of fibrosis-related proteins in DN, which might ultimately alleviate renal fibrosis." (PMID 36544775, 2022). "However, to date, the relationship and underling mechanism between IL-22 and Notch1 signaling pathway, and the exact role of IL-22 signaling pathway in the progression of renal fibrosis are not elucidated." (PMID 32338120, 2020). "Thus, we next examined whether the blockage of diabetic kidney injury by IL-22 gene therapy was mediated by inhibition of renal fibrosis." (PMID 28726774, 2017). "Our results indicated that anti-ANGPTL3/IL22 administration attenuated podocyte injury and ACR, while ameliorating renal fibrosis and regulating glucolipid metabolism by suppressing the inflammatory response." (PMID 36544775, 2022). "Weathington confirmed that IL-22, the main effect molecule of Th22 cell, can bind to the IL-22RA receptor, activating JAKI–STAT1 and STAT3 pathways, regulating Akt, ERK, JNK and p38 signal, thus participating in the regulation of renal fibrosis." (PMID 29708439, 2018).
renal fibrosis (continued). "Furthermore, absence of IL‐22 involves more tubular injury, tubular cell death and tubular atrophy, while renal fibrosis remains unaffected in vivo." (PMID 30156011, 2018).
acute pancreatitis (9 papers, 2018 to 2025). An acute inflammatory process that leads to necrosis of the pancreatic parenchyma. "The aim of this study is to assess the prognostic significance of thromboelastogram parameters, interleukin-6, and interleukin-22 levels in assessing the risk for developing severe forms of acute pancreatitis." (PMID 39694959, 2024). "Several animal model studies have reported a significant reduction in IL-22 expression and Th22 cells in lung tissues following acute pancreatitis." (PMID 40141214, 2025). "Interleukin-22 (IL-22) plays a dual role in acute pancreatitis, acting as a marker of disease severity and as a protective agent." (PMID 39694959, 2024). "At the same time, AHR activation by biliverdin, an AHR agonist, increased pancreatic IL22 levels and provided protection against acute pancreatitis." (PMID 38612627, 2024). "The study highlights that both IL-6 and IL-22 play crucial roles in the inflammatory cascade of severe acute pancreatitis." (PMID 39694959, 2024). "Based on the results, the study underscores the significant role of interleukins, particularly IL-6 and IL-22, as well as specific hemostasis parameters, in the development and prognosis of severe acute pancreatitis (SAP)." (PMID 39694959, 2024). "The aryl hydrocarbon receptor (AHR) emerges as a critical transcription factor pivotal for the production of IL22, a protective cytokine in acute pancreatitis." (PMID 38612627, 2024). "The goal of this study is to evaluate the prognostic significance of inflammatory markers (interleukin-6 and interleukin-22), their dynamics and hemostatic parameters in predicting the development of severe acute pancreatitis (SAP)." (PMID 39694959, 2024). "IL-22 is a potential indicator for monitoring organ dysfunction and severity of severe acute pancreatitis (SAP)." (PMID 38750415, 2024). "Our results confirm a potential protective role of IL-22 in acute pancreatitis, which makes it not only a prognostic marker but also a promising therapeutic agent, which requires further study." (PMID 39694959, 2024). "IL-22 has been demonstrated to be protective in acute pancreatitis, therefore a long-term blockade of these signaling pathways in patients with chronic pancreatitis could have opposing effects, especially in case of an acute pancreatitis episode." (PMID 37881430, 2023). "Using flow cytometry, the levels of IL-22+, IL-10R2+ or IL-22R1+ cells in PBMCs from PDAC patients were compared to controls and patients with other disorders, including AP, CP, alcohol-induced acute pancreatitis (AIAP), cholangitis (Cho), common bile duct stone (CBDS) and gall bladder stone (GBS)." (PMID 38643339, 2024).
airway hyperresponsiveness (9 papers, 2014 to 2025). "In particular, an increased fecal F/B ratio has been associated with elevated lung IL-17 and IL-22 responses and enhanced airway hyperresponsiveness." (PMID 38526572, 2024). "The increased ratio of Firmicutes/Bacteroidetes species as well as segmented filamentous bacteria colonization is associated with lung IL-17 and IL-22 responses and enhances airway hyperresponsiveness." (PMID 35033061, 2022). "Neutralizing IL-22 antibodies can increase the production of Th2 cytokines, causing eosinophil infiltration and airway hyperresponsiveness." (PMID 25289045, 2014). "Together, the data demonstrate that ozone exposure activates AhR, which controls lung inflammation, airway hyperresponsiveness, and tissue remodeling via the reduction of IL-22 expression." (PMID 32161582, 2020). "Ovalbumin (OVA)-induced pulmonary inflammation, immune responses, and airway hyperresponsiveness (AHR) were examined and compared between IL-22 transgenic mice and wild type controls." (PMID 25254361, 2014). "IL-22 transgenic mice showed decreased eosinophils in the BAL and a significant reduction in eosinophilic inflammation in the lung, decreased mucus metaplasia in the airways and functionally, reduced airway hyperresponsiveness." (PMID 25254361, 2014). "Furthermore, IL-22 in combination with IL-17, but neither alone, elicits airway hyperresponsiveness (AHR) in naïve mice." (PMID 34022896, 2021).
Erythema (9 papers, 2014 to 2025). Redness of the skin, caused by hyperemia of the capillaries in the lower layers of the skin. "It was also proven that LO reduced the levels of IL-1, IL-22, and IL-17 and improved symptoms of erythema, scaling and skin thickness." (PMID 36986611, 2023). "Thus, we provide an explanation of how repetitive flare-ups eventually favor the persistent erythema by inducing type I IFN–driven and IL-22–mediated neovascularization." (PMID 36633910, 2023).
hepatitis B (9 papers, 2012 to 2024). "This study was performed based on a case-control format to assess IL-22 rs1179251 single nucleotide polymorphism genotypic and allelic frequencies among 227 hepatitis B chronic patients and 227 healthy controls." (PMID 31749919, 2019). "Interleukin-22 can promote hepatocyte survival in acute mouse models of liver damage, while IL-22 recruitment of Th17 cells has been implicated in chronic liver inflammation of hepatitis B-infected individuals." (PMID 27055194, 2016). "Although generally being hepatoprotective, IL-22 actually aggravates disease in experimental hepatitis B virus infection which appears to be mediated by IL-22-driven expression of chemokines such as CXCL9 and CXCL10." (PMID 23382730, 2013). "Thus, IL-17 and IL-22 have a significant protective role to play during hepatitis B infection and in the immune response to vaccines." (PMID 39057781, 2024). "A recent report indicates that IL-22 may also amplify liver injury in experimental hepatitis B virus infection." (PMID 22967278, 2012). "As a result, IL-22 may be both proinflammatory and profibrogenic in hepatitis B. In addition, elevated circulating levels of Th22 correlated with the severity of HBV-associated acute–chronic liver failure (HBV-ACLF), suggesting that Th22 cells are a negative predictor of prognosis in HBV-ACLF." (PMID 36839448, 2023). "Moreover, IL-22 production in hepatitis B patients is positively related to the HBV load." (PMID 36839448, 2023).
Infertility (9 papers, 2021 to 2025). "IL-22 is key in order to prevent secondary infertility caused by endotoxin-induced inflammation after inflammatory-induced abortions." (PMID 36091010, 2022). "IL-22−/− mice revealed a significantly reduced ability to become pregnant (9.1% of pregnancy success) in comparison to WT mice (71.4% of pregnancy success), suggesting that IL-22 deficiency might be associated with secondary infertility." (PMID 36091010, 2022). "IL-22 has pivotal importance in the prevention of secondary infertility with inflammation and in post-inflammatory regeneration by modulating tight and adherens junctions, orchestrating ECM proteins, and providing an antibacterial barrier." (PMID 36091010, 2022). "We demonstrated that IL-22 is a potential candidate for the treatment of secondary infertility and impaired uterine regeneration due to infection and inflammation that occur during the primary pregnancy." (PMID 36091010, 2022). "Another study involving patients with unexplained RPL and unexplained infertility concludes that RPL patients have significantly higher endometrial IL-22 levels than healthy controls." (PMID 36091010, 2022). "Further in vitro studies are needed to address this and to underpin the link between IL-22, uterine endometrium regeneration, and inflammation-mediated infertility." (PMID 36091010, 2022). "This can be explained by the absence of IL-22 and its necessity to prevent secondary infertility in IL-22-deficient mice." (PMID 36091010, 2022).
lung disease (9 papers, 2010 to 2024). "Studies have shown that ILC3 play a role in pulmonary diseases through the IL-17/IL-22 axis by rapidly secreting IL-17 and IL-22, which are involved in pulmonary inflammation and infectious diseases." (PMID 35122179, 2022). "In conclusion, IL-22 is involved in a variety of lung diseases, making it a promising target for clinical development." (PMID 35967401, 2022). "Rapid secretion of IL-17A and IL-22 highlights the role of ILC3s in lung diseases, as the IL-17/IL-22 axis contributes a lot to the epithelial immunity." (PMID 33718260, 2021). "IL-22 was higher in lavage from patients with lung disease than in controls (38.0 vs 15.3 pg/ml, p < 0.001)." (PMID 27388918, 2016). "Patients with confirmed lung disease (n = 173) had significantly higher IL-22 levels in bronchoscopic lavage (BL) than the reference cohort (38 vs 15 pg/ml, p < 0.001)." (PMID 27388918, 2016). "Our aim was to study the role of Th17 cells in cystic fibrosis lung disease by measuring IL-17 protein and mRNA levels and IL-22 and IL-23 mRNA in sputum of clinically stable CF patients and by comparing these levels with healthy controls." (PMID 21143945, 2010). "Silencing IL-22 in mice-models of SSc lung disease may prove helpful to understand if IL-22 has a different role in the lung compared to the skin." (PMID 37753072, 2023). "Immunotherapeutic strategies via targeting IL-22, in lung diseases." (PMID 35967401, 2022). "IL-22 can be measured in lavage samples, and correlates with the presence of lung disease." (PMID 27388918, 2016). "In addition to the data we have presented, IL-22 has been investigated in other non-malignant lung diseases." (PMID 27388918, 2016).
malaria (9 papers, 2013 to 2024). Malaria is a serious and sometimes fatal disease caused by a parasite that commonly infects a certain type of mosquito which feeds on humans. "Koch, Rockett showed that the IL22 SNPs coexisting together (+1394A and -708T) and (-708C and +1394A) were associated with protection and vulnerability, respectively, to severe malaria." (PMID 38404582, 2024). "We found that the rs2046068 A allele in the IL-22 gene was statistically high under a dominant mode of inheritance in the malaria group within the 1-5 years age group compared to the 6 years and older age group." (PMID 32148440, 2020). "Our study supports the evidence of the role of IL-22 in the clinical manifestation of P. falciparum-associated malaria." (PMID 32148440, 2020). "In addition, studies to outline the molecular or cellular mechanisms underlying the role of IL-22 in malaria are recommended." (PMID 32148440, 2020). "Such a finding could suggest an important role for IL-22 in P. falciparum-associated malaria and pathogenesis." (PMID 32148440, 2020). "Interleukin-22 (IL-22) has been implicated in several diseases including malaria." (PMID 32148440, 2020). "In conclusion, we have shown that variants of the IL22 gene may play an important role in the pathogenesis of CM and that these variants of IL22 are associated with an aggravation of malaria." (PMID 28139719, 2017). "It is already known that IL-22 deficiency may alter the microbiome of mice and therefor may influence the course of malaria indirectly." (PMID 27311945, 2016). "Available evidence implicates IL-22 in the pathogenesis of Plasmodium infection and vulnerability to severe malaria anaemia has been shown to decrease with increased IL-22 levels." (PMID 38404582, 2024). "The levels of nine cytokines measured in plasma revealed an increase of IL-6, IFNg, IL-22 and IL12p70 in children with symptomatic malaria compared to uninfected children." (PMID 36787308, 2023). "Plasma levels of IL-22 are elevated in acute infection with Plasmodium falciparum in humans as well as in the murine malaria model Plasmodium berghei infection in C57BL/6 mice." (PMID 33692792, 2021). "The haplotype distribution analysis at the IL-22 gene demonstrated statistically significant frequencies between the control and P. falciparum-infected malaria groups." (PMID 32148440, 2020). "The first report of the involvement of IL-22 SNPs in malaria found two IL-22 SNPs in West African children infected with P. falciparum malaria; one correlated with protection against SM (rs2227491) and the second with susceptibility to CM (rs2227478)." (PMID 32148440, 2020). "Since the IL-22 level in plasma is increased in malaria, it was of interest to specify the cell type which is responsible for IL-22 production." (PMID 27311945, 2016). "Since IL-22 plays an elusive role in different immune disease or infection models it is of special interest to elucidate its role in malaria." (PMID 27311945, 2016). "Although IL22 is generally known as an actor in the proinflammatory innate immune response to infection, relatively little is known about its role in relation to malaria." (PMID 26744416, 2016). "Similar IL-22 levels are present in the blood plasma of P. falciparum-infected human individuals, further supporting the relevance of this cytokine in malaria." (PMID 27311945, 2016). "The aim of the present study was to further elucidate the function of IL-22 using experimental malaria models." (PMID 27311945, 2016). "In this study, blood-stage infection of C57BL/6 mice with PbA was used to analyse the impact of IL-22 during malaria." (PMID 27311945, 2016). "Among the candidate malaria resistance loci tested here, SNP rs2227478 in the IL22 gene showed the strongest ECA signal." (PMID 26744416, 2016).
malaria (continued). "Adoptive transfer of splenocytes from OT1 mice, that have ovalbumin specific T cell receptors, into wild type or Il22−/− recipients followed by infection with a transgenic ovalbumin-expressing malaria strain results in more antigen specific T cell proliferation in the Il22−/− recipients." (PMID 33692792, 2021). "Only a few studies have investigated the role of IL-22 SNPs in malaria." (PMID 32148440, 2020). "However, further investigations are needed to elucidate that IL-22 directly acts on hematopoietic cells expressing the IL-22Rα1 chain during malaria." (PMID 27311945, 2016). "As we did not investigate all the IL-22 gene variants, future case control studies are necessary to confirm the findings of this study and to explore additional links between IL-22 SNPs and the clinical outcome of P. falciparum-associated malaria." (PMID 32148440, 2020). "Hence this murine model was applied to elucidate the effect of IL-22 on the outcome of malaria." (PMID 27311945, 2016). "Analysis of SNPs in the IL22 gene found several weak associations with severe malaria in Gambian children but no clear cut effect while a SNP in IL1A (encoding interleukin1α) and another in IL1B (encoding interleukin-1β) showed a marginal association with susceptibility to malaria." (PMID 24312262, 2013). "Since the IL22 gene is located in proximity to the IFNG gene which is highly important for malaria, it was taken into consideration for further investigations regarding the severity of malaria symptoms in a large case-control study." (PMID 27311945, 2016). "Here we could show that the absence of IL-22 in murine malaria exacerbates cerebral malaria symptoms." (PMID 27311945, 2016).
systemic sclerosis (9 papers, 2014 to 2022). A chronic disorder, possibly autoimmune, marked by excessive production of collagen which results in hardening and thickening of body tissues. "Nevertheless, specific cytokines which were detected in such low levels in AAV were significantly elevated in systemic sclerosis: IL-4, IL-6, IL-17A, and IL-22." (PMID 31286195, 2019). "IL-22 has been reported to be involved in systemic sclerosis lesions." (PMID 25297677, 2014). "In systemic sclerosis (SSc), IL-22 synergistically works with TNFα to induce the expression of IL-8 and CCL2 in skin fibroblasts, while the simultaneous stimulation of TGF-β1 and IL-17A can lead to an up-regulation of IL-6 expression in fibroblasts from affected skin by nearly a hundredfold." (PMID 35967331, 2022).